RHOA (ras homolog family member A)
Diseases named in the same sentence as RHOA in open-access papers (continued):
Sharing a sentence is not in itself a finding about the gene and the disease.
cancer (continued). "Albeit the RHOA/ROCK pathway is actively targeted with numerous ROCK pharmacological inhibitors with a prospect to block invasion and metastasis in clinical trials, to date, none of them are approved for clinical use in cancer therapy." (PMID 36059552, 2022). "This phenomenon seems to be very striking, Rab22a-NeoF1 fusion protein may be limited in its negative recipient cancer cells as it is taken up by exosome endocytosis, and then it binds to PYK2 kinase that has a high efficiency to activate RhoA." (PMID 33568623, 2021). "Indeed, CAFs but not the cancer cells, are the major contributors of CCL5 in RhoA knockdown tumors as assessed by immunofluorescent staining and qRT-PCR." (PMID 31705019, 2019). "The increase in RhoA protein in HCC samples observed in our study may not be a direct result of reduced DLC2 expression, but could be due to cancer-related alterations in upstream factors that regulate the two genes." (PMID 18651974, 2008).
infection (103 papers, 2008 to 2025). The state of being infected such as from the introduction of a foreign agent such as serum, vaccine, antigenic substance or organism. "This study investigates the pathogenic relationship between RHOA and G. parasuis using an in vitro infection model with LLC-PK1 cells, including transcriptomic analysis to define indirect mechanisms underlying bacterial pathogenesis." (PMID 40999528, 2025). "In this study, we focused on RHOA as a host-dependent candidate gene and utilized LLC-PK1 cells as an in vitro infection model to explore the effects of RHOA knockout on G. parasuis infection and the underlying mechanisms." (PMID 40999528, 2025). "Studies of lytic infection models have implicated RhoA in multiple aspects of the HCMV life cycle, dependent on the cell type and stimulus used to activate the RhoA signaling pathway." (PMID 33824207, 2021). "Here, we found that the RhoA/Rho-associated protein kinase (ROCK)/myosin light chain (MLC) signaling pathway was activated in polarized LLC-PK cells during the early infection of PSaV Cowden strain in the presence of bile acid." (PMID 33692204, 2021). "Infection of CD4+ T cells by the human T lymphotropic virus type 1 frequently resulted in mutations of the RhoA GTP binding pocket region like RhoA C16R which elevated the GTP/GDP exchange, while others exerted opposite effects." (PMID 31319592, 2019). "Curiously, loss of RhoA, which promotes the spreading of ΔF11L-infected cells, was partially able to suppress the impact of the loss of RhoD during ΔF11L infection." (PMID 28486133, 2017). "On the invert, infection of LB1319-MEL cells with RhoA-encoding adenoviruses induced RhoA overexpression and increased levels of membrane-associated CD70." (PMID 26828592, 2016). "During infection of polarized epithelium with wild type V. parahaemolyticus, VopS efficiently translocates into host cells and inactivates RhoA, leading to cell rounding, a rapid loss in transepithelial resistance, and ultimately cell death." (PMID 26156628, 2015). "A second response is an innate immune response where Gαq-RhoA signaling acts within cells close to sites of infection, the rectal epithelial cells, to cause major changes in their size and shape to mitigate the effects of infection." (PMID 22359503, 2012). "The loss of F11 or its ability to bind RhoA did however result in significantly higher levels of GTP bound RhoA at 8 hours post infection, consistent with the presence of actin stress fibres in ΔF11L or F11-VK as compared to WR or WR-A36R-YdF infected cells." (PMID 20041165, 2009). "The loss of cell-cell adhesion during WR infection is also consistent with the known role of RhoA signalling in establishing and maintaining cell-cell contacts." (PMID 20041165, 2009). "We examined whether early dissociation of TJs induced by RVA-infection can be restored by inhibition of the associated RhoA/ROCK/MLC signaling pathway." (PMID 30224682, 2018). "Furthermore, Echo30 infection induced the activation of RhoA and RhoA targeted signaling, such as Rho-associated protein kinase (ROCK) and phosphorylation of myosin-light chain (p-MLC)." (PMID 22586486, 2012). "During the early stage of MVC infection, the RhoA/ROCK1/MLC2 signaling pathway is activated, resulting in TJ dissociation, Occludin exposure, and an increase in the permeability of the cell membrane, all of which facilitated MVC entry into host cells." (PMID 40142587, 2025). "During early infection with porcine sapovirus (PSaV), activation of the RhoA/ROCK/MLC signaling pathway induces contraction of the actomyosin ring, compromising tight junction integrity and exposing the core receptor occludin to facilitate viral spread." (PMID 40999528, 2025). "The quantification of the EdU-positive cells revealed significantly greater proliferation in the RHOA-KO cells than in the WT cells post-infection." (PMID 40999528, 2025).
infection (continued). "infection led to increased expression of raf1, rhoA, akt, indicating activation of intracellular signaling pathways involved in inflammation and tissue remodeling." (PMID 40740775, 2025). "Curiously, when we performed RhoGTPase inhibition in serum-free (in the case of RhoA, B and C inhibitor) or low serum (in the case of the Rac1 inhibitor) media, the difference in infection between shScr and shMyo9b #3-expressing U937 cells was reduced." (PMID 40167026, 2025). "The transmembrane proteoglycan Syndecan-1 and RhoA are involved in the infection process through the CD81." (PMID 39745447, 2025). "Crucially, RHOA expression was upregulated during infection, and RHOA knockout reduced bacterial adhesion and invasion, rescuing cell viability to 77.30%." (PMID 40999528, 2025). "Previous studies have demonstrated that several viruses, including EBOV, respiratory syncytial virus (RSV), rotavirus (RV), porcine pseudorabies virus (PRV), and SARS-CoV-2, hijack RhoA pathway to facilitate infection." (PMID 40821819, 2025). "This suggests that E. ictaluri infection activates RhoA, and that EseG, unlike typical GEFs, functions to inactivate RhoA, indicating a role in regulating RhoA activity during infection." (PMID 40637600, 2025). "To investigate the role of the porcine RHOA gene during G. parasuis infection, we established an in vitro lethal infection model using LLC-PK1 cells challenged with G. parasuis serotype 5." (PMID 40999528, 2025). "The RhoA signaling pathway plays a pivotal role in the infection of parasites, such as Plasmodium, Toxoplasma gondii, Cryptosporidium parvum and Theileria annulata." (PMID 41231913, 2025). "Our findings demonstrate that ZIKV and DENV-4 infections significantly activate RhoA signaling in U87-MG cells, suggesting that RhoA plays a critical role during infection, particularly in viral replication and the maturation of infectious particles." (PMID 40821819, 2025). "To address the question of the mechanism of the post infection cytoskeleton remodeling, we focused on RhoA proteins and vimentin playing important regulatory and transport roles in both epithelial and endothelial cells." (PMID 39616228, 2024). "Previous studies showed that S. aureus and S. agalactiae infection induced BMEC actin–cytoskeleton rearrangement through Rho GTPase (RhoA) regulated pathway modulation." (PMID 37833969, 2023). "In this study, we recapitulate the function and mechanisms by which PRV manipulate the host cell during infection, focusing on the role of RhoA and actin cytoskeleton." (PMID 37968757, 2023). "Using 10 nM CA, we obtained evidence that PPP activity is important for pyrin S205 dephosphorylation and inflammasome assembly in BMDMs in response to RhoA inactivation by TcdB or YopE/T during ∆yopM Yptb infection." (PMID 37787552, 2023). "To confirm our screening results, we measured the size of wild type or ipgB1 infection foci formed in mock-treated or RhoA-depleted HT-29 cells at 16 hrs postinfection." (PMID 35202448, 2022). "Using Gene Ontology and MetaCore gene expression patterns were investigated in SARS-CoV-1 and SARS-CoV-2 infections, and revealed that actin/cytoskeleton remodeling via the RhoA pathway is critical for infection." (PMID 35392098, 2022). "Altogether, these data indicate that the temporal activation of RhoA is critical and dictates the kinetics of actin scaffold formation during infection." (PMID 34903051, 2021). "As the infection progresses, the concentration of RhoA on the inclusion membrane increases, further inhibiting ARF1 activation." (PMID 34903051, 2021). "C3larvinA and Plx2A display C3-like activity, meaning each protein targets RhoA through a catalytic Q-X-E motif, and both can initiate infection in a target cell." (PMID 33289829, 2021).
infection (continued). "By contrast, infection with yopEL109A, which has partially reduced RhoA-GAP activity (about 70% of WT YopE) and normal Rac1-GAP activity, caused M cell extrusion similar to WT 37°C and had a Yptb internalization phenotype similar to WT 37°C." (PMID 34793276, 2021). "Evidence from lytic infection studies suggests that RhoA is downregulated upon HCMV interaction with EGFR at the cell surface; however, the role of RhoA in EGFR signaling during latency has not yet been demonstrated." (PMID 33824207, 2021). "RhoA activity and cell rounding is increased during infection with the EspO1/O1-2 double mutant, indicating that EspO1-2 also inhibits EspM1 GEF activity." (PMID 33572997, 2021). "Here, we demonstrated that the dissociation of TJs in polarized LLC-PK cells upon early infection of PSaV is mediated by the activation of the RhoA/ROCK/MLC signaling pathway." (PMID 33692204, 2021). "Infection with WT C. trachomatis L2 increased RhoA-GTP levels 2.9 ± 0.54-fold compared to uninfected control cells." (PMID 34903051, 2021). "RhoA activation during infection was EspG dependent as determined by RhoA immunoprecipitation with Rhoetekin." (PMID 33572997, 2021). "Adenovirus-infection increased the post-translationally modified MTs through upregulated Glu-MTs and acetylated MTs through the RhoA-dependent mechanism, which favors viral delivery to the nucleus." (PMID 32408515, 2020). "Compared with unstimulated mock infection, expression of RhoA and platelet-derived growth factor (PDGF)-B were significantly decreased after CMV infection." (PMID 31216320, 2019). "We verified the PPARs pathway-mediated generation of ANGPTL4 in BMECs in response to meningitic E. coli challenge and demonstrated for the first time that ANGPTL4-triggered ARHGAP5/RhoA/MYL5 signaling cascade contributed to the BBB disruption by the infection." (PMID 31766605, 2019). "RhoA/ROCK/MLC signaling was identified as activated at an early stage of infection, while inhibition of this pathway prevented the rotavirus-induced early disruption of TJ integrity and alteration of TJ protein distribution." (PMID 30224682, 2018). "In a recent study, Sato & Coburn found a slight elevation of RhoA protein levels in endothelial cells following infection of both virulent and saprophyte Leptospira strains." (PMID 29979677, 2018). "Env-CD4 binding was shown to trigger RhoA activation in T-cells, whereas interfering with RhoA activity resulted in reduced infection of PBMCs." (PMID 29401736, 2018). "In both endothelial cell types we tested, the fluorescence intensity of small GTPase RhoA was slightly elevated by Copenhageni (1.3- to 1.4-fold) and Patoc (1.1- to 1.2-fold) infection." (PMID 28750011, 2017). "A wide range of factors activate RhoA to cause EC permeability, and this prompted us to determine if RhoA was activated by ANDV infection of MECs." (PMID 27795403, 2016). "Purified KSHV gB also induces FAK autophosphorylation, and within minutes of infection, KSHV-induced FAK colocalizes with cytoskeleton associated vinculin and paxillin proteins as well as Src, PI3-K and RhoA-GTPase signal molecules in the infected cells." (PMID 27854239, 2016). "This suggests a role for ANDV inhibition of extracellular αvβ3 integrin responses as a means of reducing Rac1-directed barrier integrity and enhancing RhoA activation during ANDV infection." (PMID 27795403, 2016). "In this study, we evaluated ANDV infection and N protein regulation of TSCs that result in Rheb and RhoA activation in MECs." (PMID 27795403, 2016). "In ADMSCs, infection with pLV-miR-124 expression particles also significantly decreased RhoA expression at both mRNA and protein level." (PMID 26745800, 2016). "Increased expression of activated RhoA completely inhibited EC lumen formation and interestingly, infection of ECs with the microorganism, Bartonella bacilliformis, which led to RhoA activation, similarly blocked EC tube formation." (PMID 26812085, 2016).
infection (continued). "Findings presented here demonstrate a role for RhoA activation in MEC permeability during ANDV infection and also show that inhibition of RhoA blocks bradykinin-directed permeability in ANDV and HTNV-infected ECs." (PMID 27795403, 2016). "A sustained feedback activation of Src and the regulation of KSHV endocytosis depends upon the infection induced RhoA and Dia-2 (a formin family member) molecules." (PMID 27854239, 2016). "At 3 days after ANDV infection, we added RhoA inhibitors to cells 6 h prior to analysis of MEC permeability." (PMID 27795403, 2016). "Levels of RhoA-GTP and ROCK1 activity were elevated upon ARV S1133 infection, while inhibition of RhoA and ROCK1 reduced autophagy and subsequent apoptosis." (PMID 25944062, 2015). "The results of our study indicated that the expression of RhoA-GTP is dramatically increased from 12 to 30 hr post-ARV S1133 infection, and the up-regulation of phosphorylated ROCK1 also showed a similar trend." (PMID 25944062, 2015). "The infection amounts among the viruses with the different titers for protein expression were adjusted for equal expression levels in the RhoA activity assay and colony formation assay." (PMID 26209534, 2015). "Taken together, these results indicate that the RhoA effector mDia1 is activated and recruited to the membranes upon infection with Coxiella and, in addition, its function is important for C. burnetii entry into host cells." (PMID 26674774, 2015). "Because MAM7 was enriched at cell junctions and RhoA activation is capable of affecting the distribution of tight junction proteins, we studied the localization of tight junction markers during infection with V. parahaemolyticus." (PMID 25255250, 2014). "At 2 hours post infection, prior to the onset of cell lysis, RhoA activity was completely abolished in POR1 infected cells." (PMID 25255250, 2014). "Since MAM is constitutively expressed and present at the early stages of infection, its effect takes hold almost immediately and RhoA activation is detectable as early as 30 minutes post infection (the earliest time point measured here)." (PMID 25255250, 2014). "Overall, this mechanism accelerates effector-mediated functional changes in host cells, such as VopS-mediated irreversible RhoA inactivation and concomitant actin depolymerization, thus speeding up infection." (PMID 25255250, 2014). "Infections with Y. enterocolitica strains expressing YopT have shown that activated RhoA is released from the host membrane." (PMID 23390616, 2013). "RhoA activity increased in pulmonary epithelial cells in the presence of hypoxia upon infection with P. aeruginosa." (PMID 23418576, 2013). "During infection, YopT cleaves the prenyl modifications of membrane-bound RhoA, RhoG, Rac, and Cdc42." (PMID 23390616, 2013). "The infection rates of RhoA and Rac1 silenced cells were about 65% of that of the mock cells, while the infection rate of RhoA and Rac2 double-silenced cells was about 50% of that of the mock cells." (PMID 23721065, 2013). "Infection of hDPCs with both RhoA T19N and RhoA Q63L adenovirus for 48 hr blocked the effect of Wnt5a CM on adhesion and migration, while RhoA Q63L showed a similar inhibition of cell migration with or without Wnt5a." (PMID 23844260, 2013). "A clear accumulation of RhoA was found in the cytosolic fraction after infection with pYV+ or pYV+ ΔyopT pyopT compared to infection with the other strains investigated." (PMID 22792400, 2012). "Both the behavioral and innate immune response to infection require the conserved EGL-30 (Gαq)/UNC-73 (Trio RhoGEF)/RHO-1 (RhoA) signaling pathway (henceforth referred to as the EGL-30 (Gαq) pathway)." (PMID 22359503, 2012). "With its simple, well described, nervous system and a rapidly growing understanding of its immune system, C. elegans provides a model to understand the role RhoA and Gαq signaling play in coordinating behavioral and immune responses to infection." (PMID 22359503, 2012).